MIF (macrophage migration inhibitory factor)
Diseases named in the same sentence as MIF in open-access papers (continued):
Sharing a sentence is not in itself a finding about the gene and the disease.
encephalitis (5 papers, 2009 to 2025). An acute inflammatory process affecting the brain parenchyma. "Serum levels of MIF are raised in patients infected with West Nile virus and patients with high expression MIF polymorphisms were more likely to develop virus associated encephalitis." (PMID 36110852, 2022). "MIF facilitates West Nile virus neuroinvasion and replication and causes an overactive inflammatory response.High expression MIF polymorphisms associated with West Nile virus neuroinvasion/encephalitis in North American patients." (PMID 36110852, 2022). "Importantly, another study reported an association between high-expression MIF alleles and severe encephalitis in patients with WNV encephalitis." (PMID 40918112, 2025). "In fact, the existing data suggest MIF is up-regulated and plays a role in the pathogenesis of encephalitis caused by flavivirus, which may be characteristic for this particular etiology." (PMID 28646884, 2017). "Here we found a fivefold higher MIF concentration in CSF than in blood in the only encephalitis patient in whom we obtained corresponding CSF and blood samples." (PMID 19558639, 2009). "In accordance with our findings, a previous study showed that patients with encephalitis due to West Nile virus had elevated CSF MIF levels, compared with uninfected control patients." (PMID 19558639, 2009). "The two patients who died from encephalitis had high CSF MIF levels (6,937 ng/l and 14,213 ng/l), but the difference in CSF MIF between these patients and those who survived (5,042 [2,999 to 8,090] ng/l) was not statistically significant (P > 0.05)." (PMID 19558639, 2009). "Moreover, MIF were elevated in CSF from patients with encephalitis due to West Nile virus or with various neurological diseases such as multiple sclerosis and Alzheimer's disease." (PMID 19558639, 2009). "Moreover, Arjona and coworkers found that MIF levels were approximately 10-fold higher in CSF than in plasma in patients with encephalitis due to West Nile virus, indicating that MIF may be locally released during CNS infection." (PMID 19558639, 2009). "One patient with VZV encephalitis had approximately fivefold higher MIF levels in CSF than in blood (5,042 ng/l versus 1,031 ng/ml), and one patient with pneumococcal meningitis with accompanying bacteraemia had lower MIF levels in CSF than in blood (8,615 ng/l versus 10,913 ng/l)." (PMID 19558639, 2009). "However, the strongest correlation with MIF in encephalitis was found to be for CSF polymorphonuclear leucocytes and CSF lactoferrin (a matrix protein of polymorphonuclear leukocyte-specific granules), whereas the correlation with neopterin (a marker of CNS macrophage activation) was weaker." (PMID 19558639, 2009). "Also, patients with encephalitis (6,937 [3,961 to 8,353] ng/l) had higher CSF MIF than did patients without CNS infection (P < 0.01)." (PMID 19558639, 2009).
eosinophilia (5 papers, 2015 to 2022). "Likewise, cellular expansion in the peritoneal cavity provoked by infection is profoundly reduced in MIF-deficient mice, as is eosinophilia." (PMID 31708913, 2019). "We also tested the MIF-dependence of eosinophilia by administering the 4-IPP MIF inhibitor at the time of H. polygyrus infection." (PMID 31708913, 2019). "Taken together, previous observations and our current data indicate that MIF significantly contributes to tissue eosinophilia in allergic inflammation, which initiates local inflammatory responses and sustains chronic inflammation." (PMID 25647395, 2015). "Moreover, other eosinophils, T cells, macrophages, hepatocytes, and Kupffer cells release in situ macrophage migration inhibitory factor (MIF), a molecule that participates in the IL-5-driven maturation of eosinophils and tissue eosinophilia associated with S. mansoni infection." (PMID 36296298, 2022). "Exogenous MIF was able to partially restore protein levels of Chil3 and RELM-α in the peritoneal lavage fluid of MIF−/− mice, although remaining significantly below those of the wild-type mice, and no eosinophilia was elicited (data not shown)." (PMID 31708913, 2019).
esophageal cancer (5 papers, 2015 to 2025). A primary or metastatic malignant neoplasm involving the esophagus. "As a biomarker, MIF demonstrates clinical relevance for esophageal cancer." (PMID 41159021, 2025). "Therapeutically, targeting MIF remains understudied but shows early promise for esophageal cancer." (PMID 41159021, 2025). "Moreover, it was found that MIF bind to ACKR3 (atypical chemokine receptor 3) and increases esophageal cancer migration and invasion." (PMID 41159021, 2025). "There is still a great lack of information concerning the use of MIF as a target in esophageal cancer, which calls for more studies and research." (PMID 41159021, 2025). "MIF serves as a non-cognate ligand for CXCR2 and CXCR4: MIF (and CXCR4) in the TME are adverse prognostic indicators in esophageal cancer, and it can induce CXCR ligand and regulators of macrophage infiltration like CD44." (PMID 26267609, 2015).
fibrosis (5 papers, 2019 to 2023). the formation of excess fibrous connective tissue in an organ or tissue in a reparative or reactive process. "Our study demonstrates that specific MIF polymorphisms are associated with disease severity and complications of HCV-induced fibrosis in a stage- and context-dependent manner." (PMID 31370326, 2019). "MIF activity in the kidney is strongly dependent on the presence of M1 macrophages, which are predominant in the early period of injury but give way to type M2 in advanced fibrosis." (PMID 34768412, 2021). "Existing studies have shown that inhibition of macrophage migration inhibitory factor (MIF) can downregulate the expression level of ITGA10 and reduce bleomycin-induced pulmonary inflammation and fibrosis in rats." (PMID 36936416, 2023). "In previous studies, we could show that MIF exerts direct inhibitory effects on HSC activation via the CD74/AMP kinase signaling pathway and that this function is a pivotal driver of its hepatoprotective effects in the hepatotoxin-induced fibrosis models." (PMID 33525493, 2021).
helminth infection (5 papers, 2013 to 2022). "In this report, we now define the MIF-dependent populations in type 2 innate immunity, including ILC2s, eosinophils, tuft and goblet cells, as well as M2 macrophages stimulated by helminth infection." (PMID 35288645, 2022). "Collectively, MIF was shown to be an important player in intestinal immunity during helminth infection and should be added to our understanding of how protective responses towards parasites are orchestrated." (PMID 36430676, 2022). "Macrophages as well as ILC2s were demonstrated to express MIF receptor (CXCR4), suggesting MIF to be a co-factor on both cell types to activate response to IL-25 in helminth infection." (PMID 36430676, 2022). "In conclusion, the ‘multi-tasking’ atypical chemokine MIF has been shown to dramatically impact on key type 2 immune responses during helminth infection, and to do so across a range of cell types from eosinophils, M2 macrophages, goblet cells and, most strikingly, on tuft cells." (PMID 35288645, 2022). "Both ILC2s and macrophages expressed the MIF receptor CXCR4, indicating that MIF may act as an essential co-factor on both cell types to activate responses to IL-25 in helminth infection." (PMID 35288645, 2022). "The loss of eosinophils in the absence of MIF has previously been observed in both helminth infection and airway asthma models." (PMID 31708913, 2019). "Brugia malayi and Ancylostoma ceylanicum express homologues of the mammalian cytokine macrophage migration inhibitory factor (MIF), and in a Th2 environment, such as that activated by helminth infection, Brugia MIF synergises with IL-4 to induce the development of regulatory M2 macrophages." (PMID 23875042, 2013). "Immunohistochemical staining was also used to identify widespread expression of MIF in intestinal tissues in vivo; in particular, MIF was intensely expressed within the granulomas centered around immobile larvae, at the foci of the local immune response to intestinal helminth infection." (PMID 31708913, 2019).
hyperlipidemia (5 papers, 2012 to 2024). "Whereas MIF is only detectable at low levels in healthy vessels, hyperlipidemia strongly enhances MIF expression in ECs, SMCs, monocytes, and T-cells in atherosclerotic lesions, and an even further upregulation during atheroprogression suggested a role for MIF in plaque destabilization." (PMID 23720662, 2013). "Our study showed that strategies to reduce MIF levels or block its activity might improve cognitive function, but the results were no longer significant after adjusting for alcohol consumption and hyperlipidemia." (PMID 39247699, 2024). "Furthermore, the ability of MIF to stimulate oxidized LDL (oxLDL) uptake by macrophages, and its association with protease expression and a reduced PDGF-BB-induced SMC migration may further contribute to MIF’s plaque destabilizing properties in hyperlipidemia-induced atherogenesis." (PMID 23720662, 2013).
infarction (5 papers, 2018 to 2022). A localised pathological necrosis of tissue resulting from obstruction of the blood supply usually by a thrombus, an embolus, or vascular torsion. "EXO derived from MSCs overexpressing macrophage migration inhibitory factor were superior to MSC-EXO in improving heart function following infarction in rats." (PMID 34674708, 2021). "However, our study result contradicts a prior study that found that the MIF disrupts the blood–brain barrier, increasing permeability and increasing the infarction size." (PMID 35805977, 2022). "When the MIF was administered at a 10-fold lower concentration, there was no significant increase in infarction volume." (PMID 35805977, 2022).
liver cirrhosis (5 papers, 2015 to 2025). "It is well known that chronic liver disease and heart failure often coexist, i.e., cardiac dysfunction is an important complication of liver cirrhosis, but the role of MIF in oxidative/inflammatory myocardial damage during liver cirrhosis is not clear enough." (PMID 41020850, 2025). "Even in terms of compensated liver cirrhosis, and especially during acute decompensation, the composition of chemokines including MIF in the peripheral blood might be affected due to hepatic inflammation and systemic infection." (PMID 31370326, 2019). "Notably, HBV-miR-2 activated genes including inflammatory genes like P2RX7 and PYCARD, fibrosis-induced genes like ANXA2 and MIF oncogenic genes like FOS and JUN, which were further verified via RT-qPCR and highly expressed in the particular stages of CHB, liver cirrhosis and HCC." (PMID 40405227, 2025).
lymphoma (5 papers, 2007 to 2018). A malignant (clonal) proliferation of B- lymphocytes or T- lymphocytes which involves the lymph nodes, bone marrow and/or extranodal sites. "Additional investigation is required to substantiate the association of MIF with disease activity and the development of lymphomas." (PMID 17470266, 2007).
nonalcoholic fatty liver disease (5 papers, 2014 to 2023). "Lipotoxicity in nonalcoholic fatty liver disease is mediated in part by the activation of the stress kinase JNK, but whether MIF modulates JNK in lipotoxicity is unknown." (PMID 36147562, 2022).
osteoporosis (5 papers, 2011 to 2025). A condition of reduced bone mass, with decreased cortical thickness and a decrease in the number and size of the trabeculae of cancellous bone (but normal chemical composition), resulting in increased fracture incidence. "MIF-deficient mice are resistant to ovariectomy-induced bone loss and MIF transgenic mice have high-turnover osteoporosis, suggesting that MIF could mediate bone resorption during bone remodeling and balance." (PMID 21401926, 2011). "Transgenic mice overexpressing MIF exhibit high-turnover osteoporosis, while in different animal models MIF is able to enhance osteoclastogenesis through downmodulation of SDF-1 production in bone tissue and chemoattraction of circulating CXCR4+ osteoclast precursor cells (OCPs)." (PMID 34692718, 2021). "Notably, two critical signaling pathways, MIF‐(CD74+CXCR4) and LGALS9‐CD45, were identified as potential key regulators driving the progression of osteoporosis." (PMID 41404455, 2025).
Pleural effusion (5 papers, 2019 to 2025). The presence of an excessive amount of fluid in the pleural cavity. "Univariate analysis identified death related biomarkers, mainly including MIF levels, age, cavitary lesion, pleural effusion, drug-resistant, disseminated status and CRP, IL-6 and ALB." (PMID 30841876, 2019). "Interestingly, the data suggested that patients with cavitary lesion and pleural effusion had significantly higher serum levels of MIF than that of the other patients [27.5(23.2–30.5) vs. 21.6(18.0–26.5) ng/ml, P < 0.001 and 26.5(22.1–29.5) vs. 21.9 (18.5–26.9) ng/ml, P = 0.001]." (PMID 30841876, 2019). "Our previous research confirmed that molecules such as LGALS9, MIF, and RETN were significantly elevated in the MPE of LCP compared to the pleural effusion of HP." (PMID 40959273, 2025). "In liver metastasis BL T cells, granzyme family genes (GZMA, GZMH, and GNLY) were enriched, while pleural effusion BL T cells showed increased TFF3, AGR2, MGP, and MIF expression." (PMID 39955556, 2025). "According to receiver operating characteristic curve analysis, the four cytokines (MIF, MIP-3α, IL-1β, and ENA-78) had areas under the curve (AUCs) greater than 0.710 for discriminating parapneumonic pleural effusion from noninfectious pleural effusions." (PMID 33469074, 2021).
pneumococcal meningitis (5 papers, 2009 to 2026). An acute purulent infection of the meninges and subarachnoid space caused by Streptococcus pneumoniae, most prevalent in children and adults over the age of 60. "In a prospective, nationwide cohort of patients with pneumococcal meningitis, we showed high-expression MIF alleles were associated with disease severity and death." (PMID 33407905, 2021). "Our findings are in line with a previous study that described high-expression MIF alleles to be associated with disease severity and death in patients with pneumococcal meningitis." (PMID 33407905, 2021). "Functional genetic polymorphisms of macrophage migration inhibitory factor (MIF) alleles have shown to predict mortality of pneumococcal meningitis." (PMID 33407905, 2021). "Limiting the analysis to the 38 pneumococcal meningitis patients showed similar results, with higher plasma concentration of MIF on admission being associated with mortality (p = 0.039)." (PMID 33407905, 2021). "In patients with pneumococcal meningitis MIF cerebrospinal fluid (CSF) values were increased and high CSF MIF levels are associated with systemic complications and death." (PMID 33407905, 2021). "We found that in the acute illness of pneumococcal meningitis, higher plasma MIF concentrations were predictive for mortality (p = 0.009)." (PMID 33407905, 2021). "Our study confirms the role of MIF in poor disease outcome in the acute phase of pneumococcal meningitis." (PMID 33407905, 2021). "CSF MIF levels were significantly higher in patients with pneumococcal meningitis than in those with meningococcal meningitis." (PMID 19558639, 2009). "Here, we further define the role of MIF on outcome in pneumococcal meningitis." (PMID 33407905, 2021). "Both results suggest MIF modulating therapy could be an interesting new target to influence outcome of pneumococcal meningitis." (PMID 33407905, 2021). "Therefore, MIF modulation is an interesting adjunctive therapy to improve outcome of pneumococcal meningitis." (PMID 33407905, 2021). "Our study confirms the role of MIF in poor disease outcome of pneumococcal meningitis." (PMID 33407905, 2021). "The frequency of 7-CATT is also higher in patients with pneumococcal meningitis than in the general population, suggesting that the tendency for a high MIF expression is not only unfavorable during infection, but also associated with an increased risk of its development." (PMID 28646884, 2017). "Moreover, patients with pneumococcal meningitis had significantly higher CSF MIF levels than did those with meningococcal meningitis (11,569 ng/l [8,615 to 21,935] ng/l versus 5,006 [1,717 to 10,905] ng/l; P = 0.02)." (PMID 19558639, 2009). "Pneumococcal meningitis carries a higher mortality than meningococcal meningitis, and differences in bacterial virulence factors may account for higher CSF MIF levels in pneumococcal meningitis than in meningococcal meningitis." (PMID 19558639, 2009). "In one patient with pneumococcal meningitis and bacteraemia with a lung focus, high MIF levels were found both in CSF and blood, suggesting that MIF may be elevated at several sites of an infection." (PMID 19558639, 2009).
rheumatic diseases (5 papers, 2010 to 2026). "In this paper, we will focus on the function and expressional regulation of MIF in several rheumatic diseases and related conditions." (PMID 22046508, 2010). "The analysis of cell communication suggested that the MIF and GALECTIN signaling pathways play a key role in the interaction between T cells and myeloid cells in five rheumatic diseases." (PMID 42210923, 2026).
sarcoma (5 papers, 2023 to 2025). A usually aggressive malignant neoplasm of the soft tissue or bone. "The interaction between sarcoma cells and macrophages, mediated by MIF and the CD74 receptor, tends to push macrophages toward a tumour‐promoting state, thus supporting tumour growth." (PMID 39658531, 2024). "According to single-cell RNA sequencing data, sarcoma cells release MIF to adversely affect the activation status and protumorigenic potential of macrophages via CD74." (PMID 38136307, 2023). "Indeed, suppression of the MIF in sarcoma cells improved the secretomic profiles of tumor-infiltrating macrophages while increasing the rates of tumor antigen presentation." (PMID 38136307, 2023). "Similarly, MIF was highly expressed in sarcomas like in other tumours." (PMID 40045162, 2025). "Levels of IL-1β, IL-4, IL-6, CXCL5, CXCL12, CXCL14, MIF, IGF-1, TGFβ-1, and CCL21 were increased in one or more sarcoma cohorts compared with controls, and levels of IL-15 and IL-16 were significantly lower in one or more sarcoma cohorts compared to healthy controls." (PMID 41008853, 2025).
acute pyelonephritis (4 papers, 2012 to 2022). "Urinary MIF concentrations were increased in patients with acute pyelonephritis, acute renal rejection, and proliferative glomerulonephritis, and correlated with renal MIF expression and the degree of renal injury." (PMID 28813470, 2017). "In this study, we showed that elevated urinary MIF levels accompanied the development of AKI during kidney infection in patients with acute pyelonephritis (APN)." (PMID 23319831, 2012).